SEPTIN6 (septin 6)
Description:
Filament-forming cytoskeletal GTPase. Required for normal organization of the actin cytoskeleton. Involved in cytokinesis. May play a role in HCV RNA replication. Forms a filamentous structure with SEPTIN12, SEPTIN6, SEPTIN2 and probably SEPTIN4 at the sperm annulus which is required for the structural integrity and motility of the sperm tail during postmeiotic differentiation.
Synonyms: KIAA0128; SEP2; SEPT6; SEPT2; MGC16619; MGC20339; Septin-6
Tractability: Small molecule: a structure with a bound ligand is known. PROTAC: ubiquitination databases record sites on it.
Gene: Protein-coding gene on chromosome X (119,615,724 to 119,693,949, reverse strand). Ensembl gene ENSG00000125354.
Subcellular location: Cytoplasm; Cytoplasm, cytoskeleton, spindle; Chromosome, centromere, kinetochore; Cleavage furrow; Midbody; Cell projection, cilium, flagellum
Subcellular location (Human Protein Atlas): Cytosol; Mid piece; Primary cilium; Principal piece
Gene Ontology:
Molecular function: protein binding; GTP binding; GTPase activity; molecular adaptor activity
Biological process: cytoskeleton organization; cytoskeleton-dependent cytokinesis; intracellular protein localization; mitotic cytokinesis
Cellular component: septin complex; sperm annulus; cell division site; microtubule cytoskeleton; septin ring; axon terminus; cleavage furrow; cytoplasm; midbody; motile cilium; presynapse; septin collar; spindle; synaptic vesicle
Homologues: Orthologues: rabbit SEPTIN6 (99% identical), guinea pig SEPTIN6 (99% identical), pig SEPTIN6 (99% identical), dog SEPTIN6 (96% identical), mouse Septin6 (96% identical), macaque SEPTIN6 (96% identical), chimpanzee SEPTIN6 (96% identical), rat Septin6 (96% identical), zebrafish septin6 (91% identical), tropical clawed frog septin6 (89% identical), Drosophila melanogaster Septin2 (67% identical), Caenorhabditis elegans unc-61 (45% identical). Paralogues in human: SEPTIN11 (82% identical), SEPTIN8 (76% identical), SEPTIN10 (71% identical), SEPTIN14 (60% identical), SEPTIN7 (40% identical), SEPTIN5 (35% identical), SEPTIN2 (33% identical), SEPTIN1 (32% identical), SEPTIN9 (32% identical), SEPTIN3 (31% identical), SEPTIN12 (29% identical), TMEM250 (5% identical).
Diseases named in the same sentence as SEPTIN6 in open-access papers:
SEPTIN6 is named in the same sentence as 27 diseases in open-access papers, as found by Europe PMC text mining. Sharing a sentence is not in itself a finding about the gene and the disease. The quoted sentences say what the papers report.
leukemia (8 papers, 2009 to 2022). A malignant (clonal) hematologic disorder, involving hematopoietic stem cells and characterized by the presence of primitive or atypical myeloid or lymphoid cells in the bone marrow and the blood. "Septin 6 (SEPT6), a member of the septin family of GTPases, which preserves breakpoint at chromosomes Xq24, was found as a fusion partner with Leukemia gene (MLL1 or KMT2A) related to leukemia." (PMID 34926267, 2021).
prostate carcinoma (6 papers, 2016 to 2023). A carcinoma that arises from epithelial cells of the prostate gland. "Upregulation of miRNA-223-3p was demonstrated in prostate cancer tissues and cell lines and was found to target SEPTIN-6." (PMID 35158801, 2022).
non-small cell lung carcinoma (2 papers, 2021 to 2023). A group of at least three distinct histological types of lung cancer, including non-small cell squamous cell carcinoma, adenocarcinoma, and large cell carcinoma. "In human non-small-cell lung cancer lines, researchers verified that regulating proteins, e.g., lysine-specific histone demethylase 1, regulate tumor metastasis via demethylating the SEPT6 promoter, and the result is overexpressed Septin6, which activates the TGF-β1 pathway." (PMID 37508490, 2023).
Alzheimer disease (1 paper, 2025). A progressive, neurodegenerative disease characterized by loss of function and death of nerve cells in several areas of the brain leading to loss of cognitive function such as memory and language. "Septin 6 has been associated with abnormal phosphorylation in both Alzheimer’s disease and schizophrenia." (PMID 40779003, 2025).
colon cancer (1 paper, 2023). "Accordingly, both technologies reported the overexpression of STIM1, MBP, SEPTIN9, and SEPTIN10 and the downregulation of CRACR2A, ORMDL3, SARAF, SEPTIN3, and SEPTIN6 in colon cancer cells." (PMID 36900391, 2023).
liver fibrosis (1 paper, 2020). "On the other hand, septin-6 (SEPT6) promoted liver fibrosis through TGF-beta and MAP-kinase pathways." (PMID 31936541, 2020).
lymphoid leukemia (1 paper, 2024). A malignant lymphocytic neoplasm of B-cell or T-cell lineage involving primarily the bone marrow and the peripheral blood. "SEPTIN6 has been identified as a myeloid/lymphoid leukemia fusion partner." (PMID 38382674, 2024).
neutropenia (1 paper, 2022). A decrease in the number of neutrophils found in the blood. "One patient (P-01) with a variant of unknown significance in SEPTIN6 (NM_015129.5:c.1085A > G, p.(K362R)) had intermittent neutropenia for more than 3 years." (PMID 35525891, 2022).
cancer (9 papers, 2006 to 2022). A tumor composed of atypical neoplastic, often pleomorphic cells that invade other tissues. "In cancer-associated stroma, the expression of septin-2 and septin-9 was significantly upregulated, while septin-6 and septin-7 were unchanged." (PMID 32094384, 2020).
tumor (4 papers, 2020 to 2023). "The results revealed that mutations in GNAQ, SEPTIN 6, NTRK3, and IKZF1 occur only in tumor samples." (PMID 35864526, 2022).
SEPTIN6 also shares sentences with these, for which no sentence is quoted: gastric cancer (3 papers); infection (3); acute myeloid leukemia (2); hepatocellular carcinoma (2); acute lymphoblastic leukemia (1); autoimmune disease (1); breast tumours (1); ciliopathies (1); colorectal cancer (1); hypospadias (1); lung carcinoma (1); lymphoma (1); osteosarcoma (1); ovarian carcinoma (1); pancreatic cancer (1); schizophrenia (1); viral infection (1).